PFDN2 (prefoldin subunit 2)
Description:
Binds specifically to cytosolic chaperonin (c-CPN) and transfers target proteins to it. Binds to nascent polypeptide chain and promotes folding in an environment in which there are many competing pathways for nonnative proteins.
Synonyms: PFD2
Tractability: Small molecule: a structure with a bound ligand is known. PROTAC: ubiquitination databases record sites on it; its protein half-life has been measured.
Gene: Protein-coding gene on chromosome 1 (161,100,556 to 161,118,069, reverse strand). Ensembl gene ENSG00000143256.
Subcellular location: Nucleus; Cytoplasm; Mitochondrion
Subcellular location (Human Protein Atlas): Mitochondria; Nucleoplasm; Cytosol
Pathways (Reactome):
Metabolism of proteins: Prefoldin mediated transfer of substrate to CCT/TriC
Gene Ontology:
Molecular function: amyloid-beta binding; protein binding; protein folding chaperone
Biological process: negative regulation of amyloid fibril formation; positive regulation of cytoskeleton organization; protein folding; protein stabilization
Cellular component: cytoplasm; cytosol; mitochondrion; nucleoplasm; nucleus; prefoldin complex; RPAP3/R2TP/prefoldin-like complex; protein folding chaperone complex
Genetic constraint (gnomAD): Loss-of-function variants: 6 observed, 17.27 expected, observed/expected ratio (o/e) 0.35, 90% interval 0.19 to 0.69. The upper end of that interval is the gene's LOEUF score, 0.69, which puts it in group 2 of 6, group 1 being the genes least tolerant of losing a copy. Missense variants: 176 observed, 200.36 expected, observed/expected ratio (o/e) 0.88, 90% interval 0.78 to 1. Synonymous variants: 73 observed, 79.27 expected, observed/expected ratio (o/e) 0.92, 90% interval 0.76 to 1.12.
Homologues: Orthologues: chimpanzee PFDN2 (100% identical), macaque PFDN2 (100% identical), rabbit PFDN2 (99% identical), guinea pig PFDN2 (99% identical), pig PFDN2 (97% identical), dog PFDN2 (96% identical), mouse Pfdn2 (96% identical), tropical clawed frog pfdn2 (71% identical), zebrafish pfdn2 (66% identical), Drosophila melanogaster Pfdn2 (45% identical), Caenorhabditis elegans pfd-2 (30% identical).
Diseases named in the same sentence as PFDN2 in open-access papers:
PFDN2 is named in the same sentence as 19 diseases in open-access papers, as found by Europe PMC text mining. Sharing a sentence is not in itself a finding about the gene and the disease. The quoted sentences say what the papers report.
breast cancer (3 papers, 2020 to 2024). A primary or metastatic malignant neoplasm involving the breast. "Most breast cancer (BC) shows resistance to taxanes due to changes in tubulin genes, and PFDN2 is one of the neighboring proteins that can interact with sexual tubulin." (PMID 32699605, 2020). "Therefore, PFDN2 has the ability to regulate the development of resistance to Taxel treatment in breast cancer." (PMID 38612711, 2024). "For instance, dysregulated PDFN1 expression has been reported to occur in a variety of cancers, including gastric cancer, lung cancer, and colorectal cancer; increased expression of PFDN2 has been found in bladder cancer; and it has been reported that PFDN4 is highly expressed in breast cancer." (PMID 37538116, 2023).
gastric cancer (3 papers, 2023 to 2024). A primary or metastatic malignant neoplasm involving the stomach. "We previously identified PFDN2 as a novel key gene in gastric cancer (GC) based on its differential expression between cancer and normal tissues." (PMID 37538116, 2023). "Consistent with our study, other studies have reported that PFDN2 serves as an adverse prognosis marker in gastric cancer, but the function and mechanism of PFDN2 in GC progression remain unknown." (PMID 37538116, 2023). "We demonstrate here for the first time that PFDN2 could promote gastric cancer cell cycle progression, which extends the understanding of the role of the PFDN family in cancer progression." (PMID 37538116, 2023). "Previously, we identified PFDN2 as a novel key gene in gastric cancer based on its differential expression between cancer and normal tissues." (PMID 37538116, 2023). "In addition, PFDN2 increases cell cycle progression through the hnRNPD-MYBL2 pathway and may act as a potential biomarker in gastric cancer." (PMID 38612711, 2024).
bladder cancer (2 papers, 2018 to 2023). "For instance, PFDN1 can directly repress the transcription of cyclin A and thus promote lung cancer development; outlier PFDN2 expression can be detected in urine, which could serve as a biomarker for bladder cancer; PFDN5 could modulate c-MYC transcriptional regulatory activity." (PMID 37538116, 2023).
colon cancer (2 papers, 2020 to 2021). "PFDN2 is closely associated with several diseases, such as Alzheimer’s disease, colon cancer, and myelodysplastic syndromes, via different mechanisms." (PMID 34555052, 2021).
Parkinson disease (2 papers, 2015 to 2021). A progressive degenerative disorder of the central nervous system characterized by loss of dopamine producing neurons in the substantia nigra and the presence of Lewy bodies in the substantia nigra and locus coeruleus. "Moreover, knockdown of PFDN2 caused accumulation of ubiquitinated aggregated α-synuclein, a protein involved mechanistically in the pathogenesis of Parkinson’s disease through protein misfolding, formation of abnormal oligomers, amyloid fibrils and Lewy bodies." (PMID 26606528, 2015). "PFDN2 has been suggested to be involved in the pathogenesis of the most common neurodegenerative disease, Parkinson’s disease." (PMID 35111762, 2021). "miR-153–3 p microRNA downregulated α-synuclein, one protein that is associated with Parkinson’s disease, and decreased the abundance of PFDN2 in neuronal SH-SY5Y cells, suggesting a possible link between Parkinson’s disease and the prefoldin complex." (PMID 35111762, 2021).
type 2 diabetes (2 papers, 2021 to 2022). "PFDN2 was found to be associated with type 2 diabetes and predicts poor prognosis for patients with metastatic urothelial carcinoma." (PMID 36438659, 2022). "The presence of antibodies against PFDN2 is associated with an increased risk of type 2 diabetes through autoimmune activation and/or pro-inflammatory signals, which are involved in the regulation of bone homeostasis." (PMID 34555052, 2021).
hepatocellular carcinoma (1 paper, 2021). A malignant tumor that arises from hepatocytes. "Interactions between F protein in hepatitis C virus with PFDN2 promote chronic infection, which is known as a predominant risk factor for hepatocellular carcinoma." (PMID 35111762, 2021). "The alteration of one actin isoform, κ-actin, was discovered in some hepatocellular carcinoma tissues, with a decrease in its interaction with PFDN2." (PMID 35111762, 2021).
liver cancer (1 paper, 2022). An epithelial or non-epithelial malignant neoplasm that arises from the liver. "Higher expression of PFDN1 (HR = 1.49, 95% CI: 1.05–2.10, p = 0.025), PFDN2 (HR = 1.49, 95% CI: 1.05–2.11, p = 0.024), VBP1 (HR = 1.47, 95% CI: 1.03–2.08, p = 0.031), and PFDN4 (HR = 1.78, 95% CI: 1.25–2.53, p = 0.001) was significantly associated with shorter OS of liver cancer patients." (PMID 36438659, 2022).
protein misfolding diseases (1 paper, 2014). "The role of this protein in protein misfolding diseases has been investigated and prefoldin subunit 2 (PFDN2) has been implicated in AD." (PMID 24450868, 2014).
scrapie (1 paper, 2014). A fatal disease of the nervous system in sheep and goats, characterized by pruritus, debility, and locomotor incoordination. "Genes encoding proteins involved in molecular pathways that regulate protein misfolding (PSMA7, UCHL1 and PFDN2) were downregulated in scrapie-infected animals." (PMID 24450868, 2014). "Our findings reveal downregulation of PFDN2 expression in both preclinical and clinical stages of natural scrapie in the LRS of sheep." (PMID 24450868, 2014).
cancer (6 papers, 2020 to 2026). A tumor composed of atypical neoplastic, often pleomorphic cells that invade other tissues. "Immune phenotype MR analyses revealed CD64 on monocyte (FCGR1A+ monocytes) as the only immune trait causally linked to both PFDN2 and cancer risk." (PMID 41884853, 2026). "PFDN2 has the ability to regulate the folding of microtubule proteins, which when mutated or abnormal can lead to misfolding of microtubule proteins, and Taxel can inhibit cell division and slow the proliferation of cancer cells by stabilizing microtubules and destroying the mitotic spindle." (PMID 38612711, 2024). "Next, we examined PFDN2 expression in GC cell lines and found that PFDN2 was highly expressed in most cancer cells, especially HGC27 cells." (PMID 37538116, 2023). "First, we studied the role of PFDN2 only in GC, but the oncogenic role of PFDN2 in other cancers remains unknown." (PMID 37538116, 2023). "However, the role of PFDN2 in cancer initiation and progression remains unknown, especially in GC." (PMID 37538116, 2023). "Second, we demonstrated that PFDN2 could promote cancer cell cycle progression and act as an oncogene in GC, but our study could not exclude the possibility that PFDN2 contributes to cancer progression through additional mechanisms." (PMID 37538116, 2023). "PFDN2 and 6 are also present in the unconventional prefoldin RPB5 interactor (URI)-prefoldin-like complex, which has been related to several types of cancer but not LC." (PMID 32344577, 2020).
tumor (4 papers, 2020 to 2026). "There was a high correlation between PFDN2 and 4 mRNA levels in tumor samples (Spearman coefficient: 0.580; p < 0.0001) and between PFDN2 and 6 (Spearman coefficient: 0.640; p < 0.0001)." (PMID 32344577, 2020). "Our study revealed the role of PFDN2 in GC cell cycle progression and may provide a novel tumor marker and a potential target for GC." (PMID 37538116, 2023). "Tumor volume and weight were also significantly decreased in the PFDN2-KD group." (PMID 37538116, 2023).
PFDN2 also shares sentences with these, for which no sentence is quoted: Alzheimer disease (1 paper); brain tumor (1); colorectal cancer (1); head and neck squamous cell carcinoma (1); hypopharyngeal carcinoma (1); lung carcinoma (1); myelodysplastic syndrome (1).